FGF7 (fibroblast growth factor 7)
Diseases named in the same sentence as FGF7 in open-access papers (continued):
Sharing a sentence is not in itself a finding about the gene and the disease.
ovarian carcinoma (8 papers, 2022 to 2025). A malignant neoplasm originating from the surface ovarian epithelium. "Serum FGF7 protein levels above the median of 25 patients with ovarian cancer were associated with worse progression-free and overall survival (p = 0.005 and 0.019, respectively) independent of patient and tumor characteristics." (PMID 39886662, 2024). "Analysis of public databases identified associations of high FGF7 gene expression with worse ovarian cancer patient survival probability." (PMID 39886662, 2024). "Furthermore, we demonstrated that higher FGF7 levels in serum were associated with worse ovarian cancer patient outcome." (PMID 39886662, 2024). "Comparison of patient groups with serum FGF7 levels above the median versus below the median demonstrated significant association of higher serum FGF7 protein levels with worse PFS for patients with ovarian cancer (Log-rank test p = 0.005) and also with OS (Log-rank test p = 0.019)." (PMID 39886662, 2024). "Our analysis of serum FGF7 protein levels from patients with ovarian cancer found FGF7 protein expression above the median to be associated with worse progression-free survival and overall survival independent of patient and tumor characteristics." (PMID 39886662, 2024). "The FGF7 protein is expressed in 60% of ovarian cancers, as well as in normal ovarian surface epithelium." (PMID 39886662, 2024). "Treatment of ovarian cancer cell lines with FGF7 increased invasion, while an antagonistic FGFR2-IIIb antibody reduced basal and FGF7-elevated invasion." (PMID 39886662, 2024). "Our study contributes new information that FGF7 protein also has prognostic significance for patients with ovarian cancer." (PMID 39886662, 2024). "In all of these mouse models, FGF7 protein was expressed at significantly higher levels in the tumor compared to the ascites of ovarian cancer cell specimens." (PMID 39886662, 2024). "One interpretation of our observation of higher FGF7 in tumors is that once the ovarian cancer cells invaded into tissue, those cells, which were able to establish as viable tumors, needed high FGF7 expression to stimulate angiogenesis to support tumor growth." (PMID 39886662, 2024). "Our next validation step was to compare FGF7 protein levels in surgically collected tumor specimens with ascites specimens from patients with ovarian cancer." (PMID 39886662, 2024). "The absolute value of the coefficient of FGF7 in the IGCI score was the largest, indicating that FGF7 can also be used as a prognostic predictor of ovarian cancer." (PMID 35735060, 2022). "Preclinical data justifies targeting the FGF7/FGFR2 pathway in ovarian cancer." (PMID 39886662, 2024). "Furthermore, FGF7 protein is a rational candidate biomarker for prediction of ovarian cancer patient prognosis." (PMID 39886662, 2024). "In addition to this potential for developing ovarian cancer therapies targeted at FGF7/FGFR2-IIIb, FGF7 has potential for being used as a biomarker of patient prognosis and sensitivity to FGFR inhibitors." (PMID 39886662, 2024). "To evaluate whether serum FGF7 protein levels could be used to predict patient survival, we utilized 25 banked serum specimens from patients with ovarian cancer and a commercial FGF7 ELISA kit." (PMID 39886662, 2024). "We observed that the mRNA expression of fibroblast growth factor 7 (FGF7) was detected at significantly higher levels in cells of the attached tumor, compared to the ascites, of an orthotopic model of ovarian cancer using human ES-2 ovarian cancer cell line in immunodeficient mice." (PMID 39886662, 2024). "Also, the expression patterns of FGF7 and its cell-surface receptors support targeting them in ovarian cancer drug development." (PMID 39886662, 2024). "A machine learning study of RNA expression profiles found prognostic significance of elevated FGF7 mRNA with worse ovarian cancer patient survival probability; however, to date, there are no reports of FGF7 protein prognostic significance in patients with cancer." (PMID 39886662, 2024).
ovarian carcinoma (continued). "These drugs are more commonly used in the chemotherapy of lung cancer although it can be speculated that FGF7‐related regulation may also be a potential target in ovarian cancer." (PMID 35735060, 2022). "Our study demonstrated that, in addition to FGF7 mRNA, the FGF7 protein was also significantly upregulated in the tumors compared to ascites in two replicates of the mouse model, a syngeneic immunocompetent mouse model and clinical specimens collected from patients with ovarian cancer." (PMID 39886662, 2024). "Reduction of FGF7 and/or FGFR2 using shRNAi in ovarian cancer cell lines and tumors inhibited growth and increased cisplatin sensitivity." (PMID 39886662, 2024). "FGF7 (antibody: HPA043605) and CD14 (antibody: HPA001887) have higher protein content in the tissues of ovarian cancer patients, the staining of IHC sections is deeper, and the results of CD14 are more obvious." (PMID 35735060, 2022). "Based on knowledge of the FGF7/FGFR2-IIIb interaction, bemarituzumab, which specifically targets FGF7’s receptor FGFR2b, would be of particular interest and may serve as a promising agent for future use in ovarian cancer." (PMID 39886662, 2024).
prostate carcinoma (8 papers, 2007 to 2021). A carcinoma that arises from epithelial cells of the prostate gland. "Indeed, orthogonal validation of the FOS and FGF7 5′-UTR mutations in human prostate cancer cells revealed that these single-nucleotide alterations identified through PLUMAGE were sufficient to increase gene-specific transcript levels." (PMID 34244513, 2021). "Loss of the intrinsic FGF7/FGF10-type 2 FGF receptor (FGFR2) pathway and gain of the ectopic type 1 FGF receptor (FGFR1) pathway are associated with the progression to malignancy in prostate cancer (PCa) and many other epithelial originating lesions." (PMID 30761180, 2019). "Mutations that impact transcript levels were found in oncogenic genes such as FOS (chr14: 75745674, C -> G) and FGF7 (chr15: 49715462, C -> T), which are components of the MAP kinase signaling pathway and known to drive prostate cancer pathogenesis 34,35." (PMID 34244513, 2021). "Almost all members of FGFs are up-regulated in human prostate cancer, including FGF2, FGF7, FGF10 and FGF1741." (PMID 32139705, 2020).
cervical cancer (6 papers, 2008 to 2024). A primary or metastatic malignant neoplasm involving the cervix. "MiR-381 targets FGF7 in cervical cancer cells and arrests the cell cycle at the G0/G1 transition, thus inhibiting cancer cell growth." (PMID 33324542, 2020). "For example, miR-318-3p inhibits cervical cancer cell proliferation, migration, and invasion by targeting FGF7." (PMID 31815619, 2019). "Additionally, PDGF signaling elevates expression of FGF-7, which we infer may directly stimulate the cervical cancer cells, a possibility that deserves future investigation." (PMID 18232728, 2008). "These target genes were crossed with mRNAs that are downregulated by more than fivefold in cervical cancer from The Cancer Genome Atlas (TCGA) database, and 8 target genes were finally obtained (OGN, SCN7A, PGR, PTGER3, FGF7, ADAMTS5, LMO3 and ANK2)." (PMID 35513835, 2022). "In cervical cancer, miR-381 inhibits HOXA13 and FGF7, which can facilitate invasion and migration." (PMID 33324542, 2020). "Finally, they show that imatinib decreases expression of FGF-7 (keratinocyte growth factor) in CAFs, and propose that this could potentially inhibit growth of FGFR-expressing cervical cancer cells." (PMID 18232729, 2008).
ulcer (6 papers, 2014 to 2025). "The levels of mRNA encoding KGF (FGF7) were significantly lower in the skin around magnet-implanted ulcers than in the skin around simple defects." (PMID 28687753, 2017).
alopecia (5 papers, 2019 to 2026). Hair loss usually from the scalp. "Recombinant keratinocyte growth factor, also called fibroblast growth factor-7 (KGF or FGF-7), has shown a dose-dependent cytoprotective effect against CIA with cytosine arabinoside chemotherapy in mice, reducing alopecia by 50%." (PMID 39330051, 2024).
chronic obstructive pulmonary disease (5 papers, 2016 to 2020). A chronic and progressive lung disorder characterized by the loss of elasticity of the bronchial tree and the air sacs, destruction of the air sacs wall, thickening of the bronchial wall, and mucous accumulation in the bronchial tree. "Of note, in the human system FGF7 was reported to be a susceptibility locus for chronic obstructive pulmonary disease, and increased lung tissue FGF7 expression was associated with worse measures of lung function." (PMID 27905399, 2016). "Genome-wide association studies (GWASs) of a large cohort of subjects with chronic obstructive pulmonary disease (COPD) have successfully identified multiple risk genes, including fibroblast growth factor 7 (FGF7)." (PMID 30777021, 2019). "Similar patterns, including trends towards dose-dependent increases in IL-6 and also IL-1RN and FGF-7 were observed in mRNA levels from hMSCs exposed to two separate CF and one chronic obstructive pulmonary disease (COPD) BALF samples." (PMID 31553626, 2019).
colorectal cancer (5 papers, 2016 to 2024). A primary or metastatic malignant neoplasm that affects the colon or rectum. "The FGF7 signaling was reported to be disrupted in colorectal cancer, which could be a potential marker of field cancerization." (PMID 34221960, 2021). "It was demonstrated that FGF7 interacts with FGF receptor 2 (FGFR2) and promotes tumour cell invasion in colorectal cancer." (PMID 38778448, 2024). "Interestingly, FGFR2, its downstream receptor, was reported down regulated in colorectal cancer tissue compared to controls, but not in distant sites, suggesting a role of FGF7 within the peritumour microenvironment." (PMID 33670920, 2021).
epilepsy (5 papers, 2013 to 2023). A brain disorder characterized by episodes of abnormally increased neuronal discharge resulting in transient episodes of sensory or motor neurological dysfunction, or psychic dysfunction. "Similar to FGF5, FGF7 also has a putative positive role in epilepsy as Fgf7-deficient mice exhibit enhanced seizure activity." (PMID 36650549, 2023). "Furthermore, Fgf7 knockout mice have increased susceptibility to epilepsy associated with increased hippocampal neurogenesis and mossy fiber sprouting and decreased inhibitory vesicles in pyramidal neurons." (PMID 34003106, 2021). "In addition, increased neurogenesis and mossy fiber sprouting have been reported in FGF7 knock-out mice during post-SE epileptogenesis, both events that may also favor susceptibility to epilepsy development in these mice." (PMID 24062643, 2013). "FGF7-null are prone to develop epilepsy after kindling, while FGF22-null are resistant to seizure induction, providing a link between synaptogenic defects and a neurobehavioral phenotype." (PMID 24672476, 2014). "For example, mice lacking FGF7 are predisposed to epilepsy in a kindling protocol." (PMID 24672476, 2014). "Therefore, FGF7 activation may be capable of decreasing vulnerability to epilepsy by multiple mechanisms." (PMID 24062643, 2013).
pancreatic cancer (5 papers, 2008 to 2023). "FGF7, which exerts its biological effects by binding to FGFR-IIIb, was observed to promote tumor angiogenesis and migration of pancreatic cancer." (PMID 27677589, 2016). "These genes were overlapped with 9,170 DEGs in PAAD, which were obtained by comparing the mRNA expression profile between pancreatic cancer in TCGA and the normal pancreas in GTEx; six specific genes were found, including VWF, GNG11, FGF7, TNXB, IL3RA, and LPAR1." (PMID 37070074, 2023). "FGF7 and TNXB (tenascin X plays a role in organizing and maintaining the structure of muscle tissues, connective tissues, etc., by producing and assembling certain types of collagen) can increase pancreatic cancer cell migration and invasion." (PMID 37070074, 2023).
pulmonary edema (5 papers, 2013 to 2025). Accumulation of fluid in the lung tissues causing disturbance of the gas exchange that may lead to respiratory failure. "These evidences supported that FGF-7 could be a good candidate for the prevention of pulmonary injury caused by high-altitude environment, such as high-altitude pulmonary edema (HAPE)." (PMID 27444145, 2016).
COVID-19 (4 papers, 2021 to 2024). A disease caused by infection with severe acute respiratory syndrome coronavirus 2. "The distribution of FGF7 in diabetic patients with severe COVID-19 symptoms appeared wider compared to other groups." (PMID 38654010, 2024). "Our results suggest that SARS-CoV-2 specifically upregulates pancreatic FGF7 concentration relative to other tissues, implying a close correlation between FGF7 and the pancreas function under COVID-19." (PMID 38654010, 2024). "Through our analysis with ROC curves, we determined the cutoff value of FGF7 to be 13.7 pg/ml between severe and mild COVID-19 patients, to predict the infection severity." (PMID 38654010, 2024). "Furthermore, retrospective clinical data revealed that diabetic patients with severe COVID-19 symptoms exhibited elevated serum FGF7 levels compared to those with mild symptoms." (PMID 38654010, 2024). "However, in diabetic patients with COVID-19, the serum FGF7 concentration increased with severity (mild vs. severe: 10.28 ± 5.20 pg/ml vs. 19.70 ± 10.95 pg/ml, p = 0.0003)." (PMID 38654010, 2024). "In db mice, serum FGF7 levels significantly decreased under exposure to SARS-CoV-2, mirroring the decrease seen in diabetic patients with mild COVID-19 symptoms." (PMID 38654010, 2024). "A plot of the serum FGF7 concentration against age showed that 72% of nondiabetic patients with mild COVID-19 and 79% of nondiabetic patients with severe symptoms were above the 13.7 ng/ml with more elderly patients in the severe group." (PMID 38654010, 2024). "As in nondiabetic patients with mild COVID-19 symptoms, there was no significant alteration in serum FGF7 and insulin levels compared to the control." (PMID 38654010, 2024).
cyst (4 papers, 2014 to 2022). A sac-like closed membranous structure that may be empty or contain fluid or amorphous material. "With the addition of FGF7 (100 ng/ml), the epithelial tip grew to form a large cyst around 1 mm in diameter by culture day 7, and then, numerous buds occurred radially throughout the cystic surface and formed many alveolus-like tufts." (PMID 30635859, 2019). "Isolated lung epithelium cultured with FGF7 formed large cyst-like structures, whereas co-culture with FGF7 and ZSTK474 induced the formation of defined branches with an intact lumen." (PMID 25460003, 2014). "However, explants exposed to FGF7 were much larger and formed a cyst in the proximal part of the explant." (PMID 31191595, 2019).
lung carcinoma (4 papers, 2009 to 2023). "Additionally, overexpression or loss of expression of Fgf7 and of its specific receptor was reported for a variety of tumours including lung cancer." (PMID 19812696, 2009). "Fibroblast growth factor (FGF) isoforms, such as FGF4, FGF19 and FGF7, promoted epithelial-mesenchymal transition (EMT), cell proliferation and migration during cancer progression by inducing store-operated calcium entry in lung carcinoma." (PMID 33005178, 2020).
prostate tumors (4 papers, 2013 to 2025). "Prostate tumors often show downregulation of FGFR2b and KGF (FGF7) and upregulation of other FGFs and FGFRs which drive proliferative." (PMID 24199173, 2013). "CAFs isolated from prostate tumor stroma of AA patients secrete higher levels of pro-inflammatory cytokines and growth factors such as brain-derived neurotrophic factor (BDNF), VEGF, and fibroblast growth factor 7 (FGF7) compared to their EA counterparts." (PMID 34071280, 2021). "Taken together with evidence that FGF7 activates FGFR2 in FP‐RMS cells, our data strongly support this ligand‐receptor pairing forming an autocrine loop promoting FP‐RMS cell viability and survival in a similar fashion to that observed in prostate tumors and pre‐adipocytes." (PMID 34850536, 2022).
viral infection (4 papers, 2020 to 2025). "In summary, FGF7 enhanced viral infection in islet organoids while simultaneously decreasing ACE2 levels in response to SARS-CoV-2 infection." (PMID 38654010, 2024). "Over time, FGF7 appeared to enhance viral infection within islet organoids and virus release into the supernatant over time, while FGFR inhibitors effectively halted viral replication between 24 hpi and 72 hpi." (PMID 38654010, 2024). "We previously showed that FGFs suppress the interferon response and that the promotion of viral infection by FGF7 correlates with reduced expression of ISGs in HaCaT keratinocytes." (PMID 39621133, 2024). "In tissues collected from db mice, the concentrations of FGF7 in the liver and intestine remained unchanged, but the FGF7 level decreased in the lung during viral infection." (PMID 38654010, 2024). "Therefore, the beneficial effect of increased FGF7 expression, which includes promotion of tissue repair and protection from physical and chemical insults, may come with a risk of enhanced viral infections." (PMID 32720440, 2020). "Therefore, diabetic (db) and wild-type (wt) mice were inoculated with SARS-CoV-2 to study the in situ variations in FGF7 levels during viral infection." (PMID 38654010, 2024). "Moreover, FGFR inhibitors reversed the FGF7-induced reduction in ACE2 expression during viral infection (G5 group)." (PMID 38654010, 2024). "Our results suggest that FGF7 activation of the FGF7-FGFR signaling pathway increases ACE2 expression, consequently enhancing viral infection and replication in islet organoids." (PMID 38654010, 2024). "However, whether the upregulation of ACE2 induced by activation of the FGF7-FGFR pathway would be a beneficial for insulin secretion or potentially promote viral infection during SARS-CoV-2 infection remained uncertain and investigated in the following section." (PMID 38654010, 2024). "Inhibiting FGFR counteracts the FGF7-induced ACE2 upregulation, subsequently reducing viral infection and replication in the islets." (PMID 38654010, 2024). "Although FGFR inhibitors counteracted the excessive viral infection induced by FGF7 and reduced ACE2 consumption, FGFR inhibitors did not improve GSIS." (PMID 38654010, 2024). "Our findings suggest that FGF7 may enhance viral infection and replication primarily in β cells rather than in α and δ cells through ACE2." (PMID 38654010, 2024).
androgenic alopecia (3 papers, 2020 to 2025). "For instance, Gentile and Garcovich reported that adding dihydrotestosterone (DHT) to DPCs from patients with androgenic alopecia decreases the expression of FGF7 within cells while increasing the secretion of both FGF7 and FGF2." (PMID 40867641, 2025). "Its mechanism of action in improving androgenetic alopecia is potentially associated with the increased expression of EGF, FGF5, and FGF7." (PMID 33353178, 2020). "Both FGF7 and BMP are known to regulate the Wnt pathway in hair progenitor cells, suggesting that DHT-stimulated secretion of FGF7 in DPCs interacts with receptors on hair progenitor cells to inhibit the Wnt signaling pathway, ultimately contributing to the development of androgenic alopecia." (PMID 40867641, 2025).
breast tumour (3 papers, 2017 to 2021). "Importantly, recent work on breast tumours showed in vivo that reducing the production and secretion of FGF-7 by CAFs, together with other factors, could diminish cell growth and cancer progression." (PMID 34948097, 2021).
cholangiocarcinoma (3 papers, 2022 to 2024). A carcinoma that arises from the intrahepatic biliary tree (intrahepatic cholangiocarcinoma) or from the junction, or adjacent to the junction, of the right and left hepatic ducts (hilar cholangiocarcinoma). "SOX9 has been identified as a crucial regulator in cholangiocarcinoma (CCA), where it promotes plays a significant role in enhancing the expression of FGF7 and FGFR2." (PMID 38491511, 2024).